PTPRD (protein tyrosine phosphatase receptor type D)
Diseases named in the same sentence as PTPRD in open-access papers (continued):
Sharing a sentence is not in itself a finding about the gene and the disease.
gastric adenocarcinoma (5 papers, 2014 to 2022). "Clinicopathological and prognostic roles of PTPRD in gastric adenocarcinoma were investigated using immunohistochemistry with 513 paraffin-embedded gastric adenocarcinoma tissue blocks." (PMID 25412184, 2014). "The current study aimed to investigate PTPRD expression and its prognostic significance in primary gastric adenocarcinoma." (PMID 25412184, 2014). "In conclusion, we demonstrated reduced PTPRD expression in gastric adenocarcinoma and its correlation with a more malignant phenotype and poorer prognosis in a large number of clinical samples." (PMID 25412184, 2014). "The prognostic value of PTPRD for gastric adenocarcinoma patients' overall survival was evaluated between patients with high and low PTPRD protein levels." (PMID 25412184, 2014). "In the present study, we detected PTPRD expression level in gastric adenocarcinoma using quantitative real-time reverse transcription PCR (qRT-PCR), western blotting and immunohistochemistry." (PMID 25412184, 2014). "Correlation between PTPRD expression and clinicopathological parameters of 513 gastric adenocarcinoma cases." (PMID 25412184, 2014). "Meanwhile, prognostic and clinicopathological features of PTPRD were investigated in 513 gastric adenocarcinoma tissue samples." (PMID 25412184, 2014). "We confirmed that PTPRD might serve as a candidate tumor suppressor gene and prognostic biomarker in gastric adenocarcinoma." (PMID 25412184, 2014). "Thus, PTPRD may play an important role in gastric tumorigenesis and serve as a valuable prognostic marker of gastric adenocarcinoma." (PMID 25412184, 2014). "Thus, PTPRD and DOCK8 deserve more scrutiny as potential TSGs in gastric adenocarcinoma." (PMID 26205786, 2016). "However, thus far, the expression, clinical significance and biological functions of PTPRD in gastric adenocarcinoma have not been explored." (PMID 25412184, 2014). "However, the role of PTPRD in human gastric adenocarcinoma has not yet been investigated." (PMID 25412184, 2014).
head and neck squamous cell carcinoma (5 papers, 2014 to 2023). A squamous cell carcinoma that arises from any of the following anatomic sites: lip and oral cavity, nasal cavity, paranasal sinuses, pharynx, larynx, and salivary glands. "In head and neck squamous cell carcinoma, PTPRD is a known tumor suppressor and mutations lead to increased expression of signal transducer and activator of transcription 3 (STAT3)." (PMID 37731134, 2023). "Protein tyrosine phosphatase receptor type D (PTPRD) is a putative tumor suppressor in several cancers including head and neck squamous cell carcinoma (HNSCC)." (PMID 26267899, 2015).
non-small cell lung carcinoma (5 papers, 2022 to 2023). A group of at least three distinct histological types of lung cancer, including non-small cell squamous cell carcinoma, adenocarcinoma, and large cell carcinoma. "For example, in addition to PTPRD, also PTPRT mutations associate with a better outcome for non-small cell lung cancer patients that receive immune checkpoint inhibitors." (PMID 36755664, 2022). "PTPRD mutations were associated with better PFS and OS in patients with non-small cell lung cancer treated with immune checkpoint blockade, providing evidence for exploring the role of this mutation in the PMBL patients who receive immune checkpoint blockade in the era of immunotherapy." (PMID 35885481, 2022).
endometrial cancer (4 papers, 2018 to 2024). Primary or metastatic malignant neoplasm involving the endometrium (mucous membrane that lines the endometrial cavity). "We also expanded on the expression of PTPRD in endometrial cancer by measuring its expression in the blood of patients with endometrial cancer." (PMID 38339334, 2024). "Collectively, these data point towards a central role of PTPRD not only as a potential tumour suppressor gene, but also as an orexigenic mediator in endometrial cancer." (PMID 38339334, 2024). "An IHC analysis of a tissue microarray containing 43 endometrial cancer cores and 5 healthy tissue cores, each representing a different clinical case, was also used to measure PTPRD expression and cellular distribution." (PMID 38339334, 2024). "We therefore expanded on our observations on the effect of asprosin (10 nM) on PTPRD expression in four different endometrial cancer cell lines, namely ANC3A, Ishikawa, NOU-1, and RAL95-2." (PMID 38339334, 2024). "Moreover, PTPRD is significantly downregulated in endometrial cancer and GBM when compared to a healthy control group, both at the gene and protein levels." (PMID 38339334, 2024). "Thus, we demonstrate, for first time, that patients with endometrial cancer express PTPRD in their white blood cells (CD45 positive)." (PMID 38339334, 2024). "Similarly, PTPRD acts via a STAT3 pathway that is activated in endometrial cancer." (PMID 38339334, 2024).
epilepsy (4 papers, 2018 to 2022). A brain disorder characterized by episodes of abnormally increased neuronal discharge resulting in transient episodes of sensory or motor neurological dysfunction, or psychic dysfunction. "A common intronic variant in PTPRD was also associated with remission of seizures after treatment in a clinical cohort of epilepsy patients." (PMID 29649218, 2018). "Moreover, PTPRM, PPFIA1, SLC1A2, and SGCE were confirmed to be associated with epilepsy, while PTPRD, ASB5, and MCU were involved in neurological disorders." (PMID 29568349, 2018). "DLG2 belongs to the gene motif “BGNADP”, which is a network associated with ID and epilepsy, including also BTD, GALNT10, NMUR2, AUTS2, and PTPRD." (PMID 35627244, 2022).
nasopharyngeal carcinoma (4 papers, 2021 to 2025). A carcinoma arising from the nasopharyngeal epithelium. "PTPRD also provides sensitivity to radiotherapy in nasopharyngeal carcinoma cells." (PMID 39985075, 2025). "Reduced PTPRD expression has been reported in nasopharyngeal carcinoma (NPC), whereas increased PTPRD levels enhance the sensitivity of NPC cells to radiotherapy by decreasing STAT3 phosphorylation." (PMID 40166646, 2025). "Pertinently, PTPRD is downregulated in nasopharyngeal carcinoma (NPC), and PTPRD overexpression can promote the sensitivity of NPC cells to radiotherapy owing to STAT3 dephosphorylation." (PMID 35356799, 2022).
Anxiety (3 papers, 2020 to 2025). Intense feelings of nervousness, tension, or panic often arise in response to interpersonal stresses. "Notably, many of the discovered variants, including one DLGAP4 variant and PTPRD (rs832264) on chromosome 9, were associated with lower HADS-A scores, i.e., with the absence of clinical anxiety symptoms." (PMID 38328521, 2023).
autism (3 papers, 2011 to 2023). Persistent deficits in social interaction and communication and interaction as well as a markedly restricted repertoire of activity and interest as well as repetitive patterns of behavior. "PTPRD, the human counterpart of Lar, interacts with IL1RAPL1, which is implicated in mental retardation and autism." (PMID 22715409, 2012).
Cognitive impairment (3 papers, 2022 to 2024). Abnormal cognition is characterized by deficits in thinking, reasoning, or remembering. "As PTPRD mutations have been associated with brain disorders that include cognitive impairments, we evaluated whether Ptprd+/- or Ptprd-/- mice have learning and memory deficits by performing the Morris Water Maze test." (PMID 38890753, 2024). "PTPRD localisation is reported to be largely restricted to the brain, and has been implicated as having roles in neuronal cell adhesion, synapse function, neurofibrillary pathology in AD, neurodevelopmental disorders, and cognitive impairments." (PMID 35562959, 2022).
developmental delay (3 papers, 2022 to 2024). "Another group reported on a male infant with a homozygous deletion of PTPRD exhibiting various facial abnormalities along with hearing impairment and also developmental delay." (PMID 37834755, 2023).
laryngeal carcinoma (3 papers, 2015 to 2024). Carcinoma that arises from the laryngeal epithelium. "The aim of our study was to try to find a link between the studied polymorphisms of the DIAPH2, HIC1 and PTPRD genes and the risk of laryngeal cancer development." (PMID 34299935, 2021). "We hypothesized that if we showed a difference in the distribution of the polymorphisms of the DIAPH2, HIC1 and PTPRD genes studied, this would indicate a significant effect of these genetic variations on the risk of developing laryngeal cancer." (PMID 34299935, 2021). "Genetic susceptibility plays a role as well, with certain genetic polymorphisms, such as those in the DIAPH2, PTPRD, and HIC1 genes, being associated with an increased risk of laryngeal cancer." (PMID 38835555, 2024). "Statistical analysis to calculate the relationship between DIAPH2, PTPRD and HIC1 genes polymorphism and pathogenesis of laryngeal cancer." (PMID 34299935, 2021). "In our observation of genetic risk of laryngeal cancer, we considered three genes: the DIAPH2 (diaphanous related formin 2) gene, the PTPRD (protein tyrosine phosphatase receptor Type D) gene and the HCI1 (hypermethylated-in-cancer 1) gene." (PMID 34299935, 2021). "The aim of our study was to determine the relationship between genetic variations DIAPH2 (rs6620138), PTPRD (rs3765142) and HIC1 (rs9901806) and laryngeal cancer risk in 267 patients with histologically confirmed laryngeal cancer and 157 controls." (PMID 34299935, 2021). "The relationship between the genetic variation of DIAPH2, PTPRD and HIC1 genes and the genetic susceptibility to laryngeal cancer was investigated in this study for the first time." (PMID 34299935, 2021). "This study was designed to assess the association between DIAPH2, PTPRD and HIC1 SNPs and laryngeal cancer risk." (PMID 34299935, 2021). "Consequently, however, we didn’t show a significant difference in the distribution of PTPRD genotype between the study subgroup patients with laryngeal cancer and control subgroups." (PMID 34299935, 2021). "Homozygous deletion of PTPRD has additionally been reported in laryngeal cancer, suggesting that genetic aberrations affecting PTPRD function may be a common event across many cancers." (PMID 26267899, 2015). "Consequently, however, we found only a significant difference in the distribution of rs6620138 DIAPH2 between subgroups smokers and nonsmokers in the case group, HIC1 and PTPRD genotypes and alleles between the study subgroup patients with laryngeal cancer." (PMID 34299935, 2021). "The relationship between genetic variations DIAPH2 (rs6620138), PTPRD (rs3765142) and HIC1 (rs9901806) and the onset of laryngeal cancer were investigated." (PMID 34299935, 2021).
liver cancer (3 papers, 2022 to 2025). An epithelial or non-epithelial malignant neoplasm that arises from the liver. "PTPRD can inhibit liver cancer by promoting the methylation of DNA in it." (PMID 39877345, 2024).
migraine (3 papers, 2020 to 2025). "In the replication part of our study, three SNPs at RLS risk loci (MEIS1, PTPRD, and an intergenic region on chromosome 2p14) were genotyped in 233 patients with migraine and in 53 with comorbid RLS." (PMID 32918390, 2020). "In the replication portion of the study, we found that two SNPs (rs2300478 in MEIS1 and rs4626664 in PTPRD) increased the risk of RLS in the migraine cohort but only rs4626664 in PTPRD increased the risk of RLS in individuals with MoA." (PMID 32918390, 2020). "A recent genome-wide analysis revealed two novel loci associated with RLS in patients with migraine in addition to six previously identified RLS risk loci, namely, MEIS1, BTBD9 and PTPRD." (PMID 39801933, 2025). "Previous GWASs have identified six RLS risk loci (MEIS1, BTBD9, MAP2K5, PTPRD, TOX3, and an intergenic region on chromosome 2p14); however, only MEIS1 has been found to be associated with RLS in patients with migraine via candidate gene approach." (PMID 35350973, 2022).
oligodendroglioma (3 papers, 2022 to 2025). A well-differentiated (WHO grade II), diffusely infiltrating neuroglial tumor, typically located in the cerebral hemispheres. "Although oligodendrogliomas typically have the best prognosis among diffuse gliomas, a decrease in protein tyrosine phosphatase receptor type D (PTPRD) and contactin-associated protein 2 (CNTNAP2) gene expression can indicate more aggressive tumor development." (PMID 39062515, 2024). "Lower PTPRD expression was significantly associated with higher tumor grade in oligodendrogliomas and IDHmut astrocytomas (p < 0.05 between all grades, Wilcoxon rank sum test, 581 diffuse glioma cases)." (PMID 35982066, 2022). "Both PTPRD and CNTNAP2 exhibit recurrent mutations in all subtypes of diffuse gliomas, including oligodendrogliomas." (PMID 40426960, 2025). "Taken together, the data support previous reports about the tumor suppressor role of PTPRD and CNTNAP2 in diffuse gliomas and show that low CNTNAP2 expression is associated with poor overall survival especially in oligodendrogliomas." (PMID 35982066, 2022). "The survival rates were poor for oligodendroglioma cases with low expression of both PTPRD and CNTNAP2 (median 8 months, maximum 30 months)." (PMID 35982066, 2022). "Our analysis revealed that PTPRD and CNTNAP2 are recurrently altered in all diffuse glioma subtypes, also in oligodendroglioma, and low expression of these genes was associated with poor patient prognosis." (PMID 35982066, 2022). "A subpopulation of oligodendrogliomas showed low expression of PTPRD (below 10.5)." (PMID 35982066, 2022). "Our analysis provides information about aggressive oligodendrogliomas with worse prognosis and suggests that PTPRD and CNTNAP2 expression could represent an informative marker for their stratification." (PMID 35982066, 2022). "Haploinsufficiency of PTPRD drives carcinogenesis in the RCAS PDGFB/Nestin-tvA mouse model of gliomas, and facilitates the development of oligodendrogliomas." (PMID 40426960, 2025). "Maximum time-lapse from diagnosis to death was 30 months for oligodendroglioma cases with low expression of CNTNAP2 or both CNTNAP2 and PTPRD." (PMID 35982066, 2022). "In The Cancer Genome Atlas (TCGA) diffuse glioma cohort, PTPRD and CNTNAP2 expression decreased by tumor grade in oligodendrogliomas and PTPRD expression also in IDH-mutant astrocytomas." (PMID 35982066, 2022). "Our analysis of primary and recurrent oligodendrogliomas revealed rearrangements in CNTNAP2 and PTPRD genes in the recurrencies, which were originally diagnosed as secondary GBMs because they showed histological signs of tumor progression." (PMID 35982066, 2022). "Although statistical significance was not reached for PTPRD in oligodendrogliomas, poor survival rates were detected in cases with low PTPRD expression." (PMID 35982066, 2022). "PTPRD and CNTNAP2, which are recurrently altered in diffuse gliomas and show decreased expression in a subpopulation of patients, could be informative for the stratification of these aggressive oligodendrogliomas by analyzing their inactivating alterations and gene expression levels." (PMID 35982066, 2022).
prostate carcinoma (3 papers, 2007 to 2025). A carcinoma that arises from epithelial cells of the prostate gland. "Frequent gene transecting alterations were observed at the TTC28 (37.1% of 143 samples), LSAMP (31.5%), and PTPRD (23.8%) loci, which have not been extensively studied in prostate cancer, though they have been reported in callsets for certain cohorts." (PMID 35943799, 2022). "In addition to alterations in highly validated prostate cancer genes, we identified highly recurrent rearrangements near or involving genes that have not been extensively studied in prostate cancer in multiple cohorts, such as LSAMP, PTPRD, and TTC28." (PMID 35943799, 2022).
bladder cancer (2 papers, 2021 to 2022). "Consistent with our findings, a recent study reported that the interaction of PTPRD (referred to WT) with its ligand LRFN4 was related to a poor response to Atezolizumab in bladder cancer s." (PMID 34615542, 2021). "For the bladder cancer patients, median PFS of PTPRD mutations group was not different from WT (over 33.00 vs 16.00 months, HR=0.29, p=0.062)." (PMID 34615542, 2021).
childhood asthma (2 papers, 2013 to 2024). "Variants in PTPRD were reported to be associated with childhood asthma in Taiwanese population." (PMID 23829686, 2013).
cutaneous squamous cell carcinoma (2 papers, 2015 to 2016). "A similar lack of aberrant PTPRD promoter hypermethylation has also been reported in cutaneous squamous cell carcinoma, suggesting this may be an uncommon event in multiple epithelial malignancies." (PMID 26267899, 2015).
endometrioid carcinomas (2 papers, 2018 to 2021). "Moreover, deletions and mutations in PTPRD have been implicated in several tumor types, including endometrioid carcinomas in the Catalogue of Somatic Mutations in Cancer (COSMIC) database, and endometrial cancers." (PMID 33436679, 2021).
gestational diabetes (2 papers, 2016 to 2024). Carbohydrate intolerance first diagnosed during pregnancy. "PTPRD is involved in insulin signaling and variants within this gene were found to be associated with gestational diabetes risk." (PMID 38195585, 2024). "Upregulated in Jamaican fruit bat cells, PTPRD, which is involved in insulin signaling and associated with gestational diabetes risk, also displayed high centrality in the Jamaican fruit bat." (PMID 38195585, 2024). "We sought to determine the influence of the PTPRD variants on the gestational diabetes mellitus (GDM) risk." (PMID 27738328, 2016).
Hypertension (2 papers, 2023 to 2024). The presence of chronic increased pressure in the systemic arterial system. "In conclusion, our data imply that only the rs10739150 genotype of the PTPRD gene shows an increased risk of hypertension, and the G allele is strongly related to the disease development." (PMID 38935682, 2024). "PTPRD TTC genetic haplotypes were strongly linked with hypertension (P = 0.003, OR = 4.03)." (PMID 38935682, 2024). "This study provides a comprehensive understanding of the involvement of rs10739150 within the PTPRD gene in hypertension." (PMID 38935682, 2024).
Insulin resistance (2 papers, 2022 to 2023). Increased resistance towards insulin, that is, diminished effectiveness of insulin in reducing blood glucose levels. "Overexpression of PTPRD in preadipocytes (3T3L1) inhibits adipogenesis, but this may lead to the development of adipose ectopic accumulation and insulin resistance, favoring the development of T2DM." (PMID 37955008, 2023).
kidney cancer (2 papers, 2017 to 2025). Primary or metastatic malignant neoplasm involving the kidney. "Meanwhile, PTPRD is implicated in the progression of kidney cancer." (PMID 40069600, 2025). "Particularly in kidney cancer, homozygous deletions are very rare: we only detect 25 in 73 cases, 3 of which overlap PTPRD." (PMID 29089486, 2017).
memory impairment (2 papers, 2021). "Deleting one of the PTPRD alleles in mice leads to memory impairment and altered electrophysiological responses in the hippocampus." (PMID 33920310, 2021). "Although there is no information on how these variants affect the expression of PTPRD, mouse models deficient for PTPRD show impairments in learning and memory tasks, which is relevant for OCD, since memory impairments have been previously reported in OCD patients." (PMID 34966732, 2021).
metabolic syndrome (2 papers, 2022 to 2025). A cluster of metabolic risk factors for CARDIOVASCULAR DISEASES and TYPE 2 DIABETES MELLITUS. "In the metabolic syndrome sub-network, five genes had high degrees of connection and could be considered hub genes: PTPRD, DCC Netrin 1 Receptor (DCC), Proprotein Convertase Subtilisin/kexin Type 6 (PCSK6), Unc-13 Homolog C (UNC13C), and Contactin 4 (CNTN4)." (PMID 35121771, 2022).